KLK5 (kallikrein related peptidase 5)
Diseases named in the same sentence as KLK5 in open-access papers (continued):
Sharing a sentence is not in itself a finding about the gene and the disease.
hepatocellular carcinoma (3 papers, 2018 to 2022). A malignant tumor that arises from hepatocytes. "lncRNA that is highly expressed in hepatocellular carcinoma exhibits oncogenic activities in esophageal carcinoma by upregulating the kallikrein-related peptidase 5 (KLK5) gene through sponging miR-185." (PMID 36287119, 2022). "By analogy, DPP4 is shed from the surface of CD4+ T cells by kallikrein-related peptidase 5 (KLK5), and in hepatoma cells Serpin B3 induces overexpression of inactive DPP4." (PMID 33143089, 2020).
inflammatory skin disorders (3 papers, 2014 to 2025). "Current knowledge on the physiological function(s) of the KLK5 protease is restricted to its central role in the regulation of skin desquamation, while its hyperactivation has been causally linked to severe overdesquamating and inflammatory skin disorders." (PMID 24158494, 2014).
oral cancer (3 papers, 2019 to 2025). "In HSIL samples, we found significant overexpression of KLK5, KLK7 and their inhibitor LEKTI, which is consistent with reports in other cancers, such as colon and oral carcinomas." (PMID 40753921, 2025).
ovarian tumor (3 papers, 2001 to 2020). "Univariate survival analysis revealed that patients with ovarian tumours positive for KLK5 expression had an increased risk for relapse and death (P = 0.018 and 0.022, respectively)." (PMID 11237385, 2001). "There, KLK5 antigen levels were significantly higher in ovarian tumor tissue than in LMP tumors." (PMID 31307411, 2019). "Preliminary RT-PCR analysis has indicated that KLK5 is expressed in a subset of ovarian tumours." (PMID 11237385, 2001). "Within our recent project, we observed robust mRNA expression patterns of KLK5 and KLK7 (this study) in the majority of ovarian tumor tissues, which were in line with data from The Cancer Genome Atlas (TCGA)." (PMID 33087135, 2020).
Pruritus (3 papers, 2015 to 2023). Pruritus is an itch or a sensation that makes a person want to scratch. "KLK5 can activate protease-activated receptor (PAR)-2, a GPCR expressed in a variety of skin cells, including sensory nerves, keratinocytes, and mast cells, which are thought to be involved in the elicitation of pruritus." (PMID 37555911, 2023). "Increased expression of KLK5 (as seen in AD) augments PAR-2 (protease activated receptor-2) activation, which is directly related to TSLP and IL-8 induction, resulting in epidermal inflammation and pruritus." (PMID 26717000, 2015).
psoriasis (3 papers, 2016 to 2025). An autoimmune condition characterized by red, well-delineated plaques with silvery scales that are usually on the extensor surfaces and scalp. "Kallikreins (like KLK5) were found in the serum of patients with psoriasis which suggests that they might be involved in the pathogenesis." (PMID 36699407, 2022).
renal carcinoma (3 papers, 2011 to 2018). A carcinoma arising from the epithelium of the renal parenchyma or the renal pelvis. "KLK expression is cell- and tissue-dependent, and although KLK6 and KLK7 have been suggested to promote tumor cell invasion, loss of KLK5 has been observed in prostate, lung, breast, testicular, and renal cancer tissues versus their normal counterparts, similar to our PDAC data presented herein." (PMID 22203845, 2011). "KLK5 is also found to be down-regulated in pancreatic, prostate, lung, testicular, and renal cancers, pointing to a tumor suppressor function." (PMID 25593998, 2014). "KLK5 and KLK6 are decreased in all three types of the renal carcinomas." (PMID 29707153, 2018).
serous ovarian cancer (3 papers, 2019 to 2020). "Hence, to further specify the clinical value of KLK5, we have now analyzed KLK5 mRNA expression and its association with patients’ outcome in a defined OC subgroup, advanced high-grade serous ovarian cancer (HGSOC)." (PMID 31307411, 2019). "In the study presented here, we analyzed the clinical relevance of KLK5 mRNA expression in a cohort including exclusively patients suffering from high-grade serous ovarian cancer (HGSOC) stage FIGO III/IV." (PMID 31307411, 2019). "In this study, we have analyzed the KLK5 mRNA expression pattern in tumor tissue of patients suffering from high-grade serous ovarian cancer stage FIGO III/IV." (PMID 31307411, 2019). "Recently, we have analyzed KLK5 mRNA expression by quantitative polymerase chain reaction (qPCR) in a homogenous cohort encompassing only patients afflicted with advanced high-grade serous ovarian cancer." (PMID 33087135, 2020). "Therefore, it is not too surprising that we observed indication for coordinate expression of some KLKs such as KLK6/KLK8 (Spearman correlation of mRNA levels: rs = 0.636;), KLK10/KLK11 (rs = 0.647;), or KLK5/KLK7 (rs = 0.568; unpublished results) in advanced high-grade serous ovarian cancer." (PMID 30811511, 2019).
alopecia (2 papers, 2017 to 2022). Hair loss usually from the scalp. "Nevertheless, Klk5-/-Klk7-/-Sp5A135X/A135X showed alopecia and growth retardation 2–4 weeks after birth, which disappeared with age." (PMID 28095415, 2017). "In the top 10 down-regulated DEGs, KLK5 (kallikrein related peptidase 5) and TCEA3 (transcription elongation factor A3) were 10 and sixfold lower in alopecia males than normal males, respectively." (PMID 35413801, 2022).
endometrial cancer (2 papers, 2021). Primary or metastatic malignant neoplasm involving the endometrium (mucous membrane that lines the endometrial cavity). "Higher expression of KLK family members 5–8 (KLK5–8) was associated with a more aggressive clinicopathologic phenotype and worse prognosis in endometrial cancer (EC) patients." (PMID 34552064, 2021). "Knockdown of matriptase in endometrial cancer cells inhibits migration and invasion ability in vitro, and our recent work showed that CRISPR-mediated disruption of KLK5 blocks OSCC cell migration." (PMID 34503205, 2021).
eosinophilic esophagitis (2 papers, 2025). Eosinophilic esophagitis (EoE) is a chronic, allergic disease of the esophagus characterized clinically by symptoms of esophageal dysfunction (including vomiting, dysphagia, feeding disorders, food impaction and abdominal pain) which persist after treatment with proton pump inhibitors (PPIs). "SPINK7 deficiency results in the unleashing of proteolytic activities and proinflammatory innate responses in oesophageal epithelium through regulating uPA and kallikrein 5 (KLK5), which makes significant contributions to eosinophilic esophagitis (EoE) pathogenesis." (PMID 40147022, 2025).
epithelial ovarian tumor (2 papers, 2011 to 2019). "Similar results were observed when KLK5 antigen levels, determined by ELISA, were compared in extracts of epithelial ovarian tumor tissue and of low malignant potential (LMP) tumors." (PMID 31307411, 2019).
influenza (2 papers, 2022 to 2026). An acute viral infection of the respiratory tract, occurring in isolated cases, in epidemics, or in pandemics; it is caused by serologically different strains of viruses (influenzaviruses) designated A, B, and C, has a 3-day incubation period, and usually lasts for 3 to 10 days. "KLK5 was found to enhance influenza and human betacoronavirus (including SARS-CoV-2) infection via cleave and activate their surface glycoprotein." (PMID 41505524, 2026). "SPINK6‐specific inhibition of HAT, and its native target KLK5 and KLK12, as well as its upregulation upon infection, underscores the importance of SPINK6 in human influenza infection." (PMID 34826211, 2022). "KLK5 and HAT are significantly upregulated in airway organoids upon H1N1/pdm infection, suggesting the importance of these proteases in the human airway during influenza infection." (PMID 34826211, 2022).
testicular cancer (2 papers, 2011 to 2019). A primary or metastatic malignant neoplasm that affects the testis. "Finally, in testicular cancer, the down-regulation of KLK5 gene expression in tumor tissues is associated with later stage and more invasive tumors." (PMID 21906360, 2011).
Ascites (1 paper, 2011). Accumulation of fluid in the peritoneal cavity (between the layers of the peritoneum that lines the abdomen). "As such, groups KLK5/10 and KLK6/10 had a marked reduction in the incidence of ascites and a corresponding longer survival." (PMID 22102857, 2011).
asthma (1 paper, 2023). "The only GWAS of T2-low adult asthma (n = 1350) revealed a genome-wide significant association (rs117639512, OR for A allele = 0.33, p-value = 2.75 × 10−8) in the intergenic region between kallikrein-related peptidase 4 (KLK4) and kallikrein-related peptidase 5 (KLK5) genes." (PMID 37761964, 2023).
benign breast tumors (1 paper, 2011). "This down-regulation of KLK5 expression may be considered as an independent novel biomarker for the differential diagnosis between the malignant and benign breast tumors." (PMID 21906360, 2011).
breast tumors (1 paper, 2011). "Subsequently, advanced biostatistics were applied in order to analyze the KLK5 expression profile in the two patients' cohorts and also to evaluate its clinical significance for the discrimination of breast tumors." (PMID 21906360, 2011). "In the present study, we have analyzed the KLK5 expression levels in malignant and benign breast tissues, with the intension to assess its clinical value for the discrimination of the cancerous from the non-cancerous breast tumors and its association with the prevalence of the disease." (PMID 21906360, 2011).
chromophobe renal cell carcinoma (1 paper, 2018). Chromophobe renal cell carcinoma is a rare subtype of renal cell carcinoma, originating from the intercalating cells of the collecting ducts and macroscopically manifesting as a well-circumscribed, highly lobulated, solid tumor that is usually diagnosed at an early stage. "Chromophobe renal cell carcinoma had increased expression of the following KLKs: KLK1 (32-fold), KLK2 (12-fold), KLK3 (69-fold), KLK4 (234-fold), KLK15 (132-fold), whereas decreased expression of KLK5 (5-fold), KLK6 (13-fold), and KLK7 (26-fold)." (PMID 29707153, 2018).
diabetes (1 paper, 2022). "In patients with type 2 diabetes, kallikrein-related peptidase 5, an enzyme responsible for the shedding of DPP4 from cell membrane, was induced in CD4+ T cells, suggesting that immune cell-derived DPP4 is responsible for reduced incretin effect in diabetes patients." (PMID 35309368, 2022).
head and neck squamous cell carcinoma (1 paper, 2014). A squamous cell carcinoma that arises from any of the following anatomic sites: lip and oral cavity, nasal cavity, paranasal sinuses, pharynx, larynx, and salivary glands. "Correlative studies have already provided evidence that five other protein members of KLK family (KLK4, KLK5, KLK7, KLK8, and KLK10) were abundantly expressed in head and neck squamous cell carcinoma, showing diagnostic value." (PMID 24669031, 2014).
hypospadias (1 paper, 2020). Hypospadias is the displacement of the urethral meatus on the ventrum of the penis. "This region on chromosome 19 is characterized by clusters of sialic acid-binding Ig-like lectin (SIGLEC) and kallikrein (KLK) genes, among which we identified likely causal relationships with hypospadias (CD33/SIGLEC3, SIGLEC5, SIGLEC7, KLK5, KLK7, KLK10, KLK13, and KLK14)." (PMID 32728162, 2020).
injury (1 paper, 2015). Damage inflicted on the body as the direct or indirect result of an external force, with or without disruption of structural continuity. "In the present study, KLK-5 expression was reduced in all asphyxiated newborns; KLK-5 promotes extracellular matrix degradation and neovascular sprouting by increasing MMP-9 activity, which, as previously noted, may contribute to brain injury." (PMID 25996847, 2015).
invasive breast carcinoma (1 paper, 2014). A carcinoma that infiltrates the breast parenchyma. "The MDA-MB-231 invasive breast cancer cell line was stably transfected with KLK5 cDNA to express physiological levels of the KLK5 mRNA and protein." (PMID 25593998, 2014).
leiomyoma (1 paper, 2023). A well-circumscribed benign smooth muscle neoplasm characterized by the presence of spindle cells with cigar-shaped nuclei, interlacing fascicles, and a whorled pattern. "Another noteworthy ECM-regulating gene is KLK5 which was differentially overexpressed in mutated leiomyomas but not in the non-mutated specimens." (PMID 36835153, 2023).
lung adenocarcinoma (1 paper, 2019). A carcinoma that arises from the lung and is characterized by the presence of malignant glandular epithelial cells. "We further show that genetic targeting of KLK5, a known target of PRSS3/mesotrypsin, phenocopies the effect of PRSS3/mesotrypsin knockdown, and also that elevated expression of KLK5 is similarly prognostic for outcome in lung adenocarcinoma." (PMID 30755669, 2019). "Here we implicate a signaling pathway consisting of PRSS3/mesotrypsin and kallikrein-related peptidase 5 (KLK5) in lung adenocarcinoma malignancy." (PMID 30755669, 2019). "These experiments implicate a potential PRSS3/mesotrypsin-KLK5 signaling module in lung adenocarcinoma and reveal the potential therapeutic benefit of selectively targeting these pathways." (PMID 30755669, 2019).
melanoma (1 paper, 2013). A malignant, usually aggressive tumor composed of atypical, neoplastic melanocytes. "Compared to melanomas without ulceration, ulcerated melanomas were characterised by downregulation of members of the kallikrein serine protease family (i.e., KLK7, KLK5, KLK11), which are related to angiogenesis and the degradation of extracellular matrix components." (PMID 23383013, 2013).
neuropathic pain (1 paper, 2016). Chronic pain caused by damage to nerve fibers. "Of the 47 investigated proteins, 21 (cathepsin S, CCL2, CCL4, CCL16, CFIII, CXCL5, cystatin B, E-Selectin, Fas/TNFRSF6, follistatin, GDF-15, GH, ICAM1, IL8, KLK5, MMP2, MMP9, P-Selectin, sortilin, TIMP4 and VEGF) were detectable by multiplex SP-PLA in ≥ 95% of the neuropathic pain patient samples." (PMID 26914813, 2016).
prostate tumors (1 paper, 2011). "On the other hand, higher levels of KLK5 expression were detected more frequently in less aggressive forms of prostate tumors, while recent findings have demonstrated the clinical use of KLK5 expression as a biomarker for the prediction of prostate patients' response to chemotherapy." (PMID 21906360, 2011).
squamous intraepithelial lesions (1 paper, 2025). "In this study, we demonstrated that the expression of serine proteases matriptase, KLK5, KLK7, and their inhibitors, HAI-1 and HAI-2, is dysregulated in human biopsies of high-grade squamous intraepithelial lesions (HSIL)." (PMID 40753921, 2025).
urothelial bladder carcinoma (1 paper, 2018). "In urothelial bladder carcinoma, increased expression of KLK5, 6 and 8 was associated with increased mortality with hazard ratios of 1.89, 1.71, and 1.60, respectively." (PMID 29707153, 2018).
tumor (43 papers, 2001 to 2025). "The combination of KLK5 + KLK7 mRNA was found to be significantly associated with residual tumor mass (p = 0.041), which was previously also observed for KLK5 mRNA alone." (PMID 33087135, 2020). "In line with the proposed signaling functions, we recently demonstrated that KLK4, in combination with KLK5, 6, and 7, regulates gene expression of other tumor-relevant genes such as MSN (encoding moesin), KRT7 and KRT19 (encoding keratins 7 and 19)." (PMID 30811511, 2019). "We conclude that KLK5 expression is associated with more aggressive forms of epithelial ovarian carcinoma and has indepdent prognostic value in low grade tumours." (PMID 11237385, 2001). "For instance, tumor-derived granulocyte colony-stimulating factor release or kallikrein-related peptidase 5 over-expression in tumor cells was found to be associated with high pre-treatment NLR, which was associated with poor prognosis in patients with uterine cervical cancer." (PMID 35597954, 2022). "KLK5 may also affect the extracellular proteolytic network in the tumor cell microenvironment by activating the zymogen forms of other tumor-associated proteases including pro-urokinase-type plasminogen activator (pro-uPA) and pro-KLK11." (PMID 31307411, 2019). "Interestingly, KLK5–7 expression in EOC tissues displayed a closer association with a larger remaining tumor following surgery, higher grade and later stage disease than CA125, the currently used biomarker for women with this cancer." (PMID 24043563, 2014). "Moreover, KLK5 targets a broad range of substrates such as insulin-like growth factor binding proteins, transforming growth factor (TGF-β), and protease-activated receptors (PAR), which upon (in-)activation by KLK5 modulate important tumor-associated signaling pathways." (PMID 31307411, 2019). "Bulk RNA-seq analysis from lesions of transgenic mice expressing oncogenes related to HPV infection revealed that Klk5 and Klk7 regulate Klk14 expression, which activates RhoA and NF-κB signaling pathways, thereby promoting tumor progression." (PMID 40753921, 2025). "KLK5, a serine protease, is a known tumor-suppressor whose activation is a promising anticancer therapy via repression of the mevalonate pathway." (PMID 41048341, 2025). "The tumor inhibition effect of KLK5 in metaplastic TNBC and its relationship with clinical characteristics need to be verified with a large number of clinical specimens." (PMID 38090381, 2023). "Some of the upregulated genes such as CXCL13 and CXCL11 and KLK5 have been experimentally verified in prior studies to regulate humoral immune response and support tumor infiltration." (PMID 37697300, 2023). "Using cell function assays, we uncovered that let-7g-5p inhibits the oncogenic role of IGF2BP3 in tumor progression, and regulates the activity of the KLK5/PAR2/AKT axis in GBC." (PMID 36313631, 2022). "Loss of CRNN expression has been associated with advanced tumor stage, whereas high expression of KLK5 has been positively correlated with tumor invasion." (PMID 35976902, 2022). "Next, we measured the mRNA levels of KLK5 in the tumor and peritumoral tissues of human GBC, and investigated the relationship between IGF2BP3 and KLK5 from a clinical perspective." (PMID 36313631, 2022). "The normalized transcript levels of KLK5, 6, 7, 8, 10, 11, and 12 genes were elevated in tumor samples, compared to normal ones while levels of KLK1, 3, 4, 13, and 15 were found to be lower in tumors, compared to normal tissues." (PMID 34065672, 2021). "Using OVMZ-6 OC cells simultaneously overexpressing KLK4–7, we observed that KLK5 in concert with the other three KLKs leads in vitro to an induction of TGFß-1 signaling, increased invasion, and chemoresistance as well as enhanced tumor burden in vivo." (PMID 31307411, 2019). "A highly significant correlation between the mRNA expression levels and protein levels of KLK5 in tumor tissues was observed (rs = 0.683, p < 0.001)." (PMID 31307411, 2019).